PVT1 (Pvt1 oncogene)
Diseases named in the same sentence as PVT1 in open-access papers (continued):
Sharing a sentence is not in itself a finding about the gene and the disease.
acute kidney injury (8 papers, 2011 to 2025). Sudden and sustained deterioration of the kidney function characterized by decreased glomerular filtration rate, increased serum creatinine or oliguria. "Moreover, PVT1 knockdown targets miR124 to improve vancomycin-induced acute kidney injury through the activation of NF-κB signaling." (PMID 34563213, 2021). "A recent study showed that lncRNA PVT1 participates in LPS-induced septic acute kidney injury." (PMID 34563213, 2021). "si-PVT1 diminished levels of TNF-α, IL-6 and IL-1β in lipopolysaccharide-induced HK-2 cells, thus alleviating inflammation and acute kidney injury." (PMID 34775377, 2021). "Overexpressed PVT1 can enhance the expression of IL-6 and IL-1β in a nonbinding manner by regulating the nuclear factor-κB (NF-κB) pathway, which is considered a critical mechanism in the regulation of immune and inflammatory processes, and ultimately aggravating septic acute kidney injury." (PMID 31304055, 2019).
esophageal squamous cell carcinoma (8 papers, 2017 to 2025). Esophageal squamous cell carcinoma (ESCC) is a type of esophageal carcinoma (EC) that can affect any part of the esophagus, but is usually located in the upper or middle third. "Recent studies have shown that circRNAs derived from the Plasmacytoma Variant Translocation 1 (PVT1) gene (circPVT1) regulate 5-fluorouracil (5-FU) chemosensitivity in esophageal squamous cell carcinoma (ESCC) by modulating the Wnt/β-catenin pathway through the miR-30a-5p/FZD3 axis." (PMID 40649179, 2025). "In this study, it was identified as a pan AC discriminative gene, which leads us to anticipate that PVT1 may be more relevant to the AC type than the SCC type, even though PVT1 has also been verified in the literature to associate with the SCC cancer type such as esophageal squamous cell carcinoma." (PMID 33318305, 2020). "The role of the long non-coding RNA PVT1 in esophageal squamous cell carcinoma remains unsolved." (PMID 28404954, 2017). "The influence of miRNA expression on mRNA–lncRNA crosstalk has been studied in esophageal squamous cell carcinoma (ESCC), comparing two intrinsic subtypes and identifying the “loss” of miR-186-mediated PVT1–mRNA and miR-26b-mediated LINC00240–mRNA crosstalk as driver events of ESCC development." (PMID 33322692, 2020).
renal cell carcinoma (8 papers, 2020 to 2025). "Previously, PVT1 promoter 5mC hypomethylation was found to be associated with worse prognosis in renal cell cancer due to PVT1-MYC upregulation." (PMID 40265030, 2025). "LncRNA PVT1 (plasmacytoma variant translocation 1) was discovered through studies conducted on renal cell carcinoma cells, where it was found to be overexpressed and highly dysregulated compared to other solid tumors." (PMID 38002304, 2023). "Our results show not only the diagnostic but also the therapeutic potential of PVT1 in renal cell carcinoma." (PMID 35441392, 2022). "The prominent association of PVT1 with renal cell carcinoma has been outlined repeatedly in lncRNA profiling studies." (PMID 33947142, 2021). "LncRNA PVT1 (plasmacytoma variant translocation 1) has become a staple of the lncRNA profile in patients with renal cell carcinoma (RCC)." (PMID 33947142, 2021). "Using qPCR, we measured the expression of PVT1 in three renal cell carcinoma cell lines (ACHN, Caki‐2, and 786–0)." (PMID 35441392, 2022). "By down-regulating miR-16-5p, lncRNA PVT1 promoted the invasion, proliferation, and epithelial-mesenchymal transformation of renal cell carcinoma cells." (PMID 34193046, 2021). "Since then, PVT1 has repeatedly emerged in many profiling studies as a prominently dysregulated lncRNA in renal cell carcinoma, even in comparison with other human tumors." (PMID 33947142, 2021). "Using search terms (“PVT1” and “renal” “and “cell” and “carcinoma”) and excluding studies that were not primarily focused on renal cell carcinoma patients or working with non-RCC cell lines, we identified 17 articles relevant for further discussion." (PMID 33947142, 2021). "An example of PVT1-MYC upregulation without 8q24 amplification was demonstrated to be the result of PVT1 promoter hypomethylation in renal cell cancer and not extra copies of the genes as seen in mammary glands tumors." (PMID 32117705, 2020).
atherosclerosis (7 papers, 2021 to 2024). A disease characterized by the build-up of fatty material and calcium deposition in the arterial wall resulting in partial or complete occlusion of the arterial lumen. "lncRNA PVT1 promotes LEASO occurrence and progression and is related to atherosclerosis severity." (PMID 37744231, 2023). "PVT1 has not been previously associated with SR; nevertheless, the mechanism underlying VSMC phenotypic switching is common to SR, atherosclerosis, artery dissection, and aneurism formation." (PMID 35328496, 2022).
esophageal adenocarcinoma (7 papers, 2019 to 2025). A malignant tumor with glandular differentiation arising predominantly from Barrett mucosa in the lower third of the esophagus. "For example, it has been reported that overexpression of PVT1 is relevant to poor prognosis of esophageal adenocarcinoma." (PMID 34586751, 2021). "In our previous study, PVT1 was identified as a subtype-specific prognostic gene for esophageal adenocarcinoma using a feature selection algorithm called the Cox-filter method." (PMID 33318305, 2020). "High expression of AZIN1-AS1, COX6C, MMP12 and PVT1 might be associated with a worse survival outcome both in TCGA ESCC and esophageal adenocarcinoma (EAC) datasets." (PMID 40569942, 2025). "In the previous study, we also discovered a positive regulation and feedback between PVT1 and YAP1 in esophageal adenocarcinoma, which is involved in tumor development, growth, and homeostasis." (PMID 33076512, 2020). "Research focused on Barrett’s esophagus and esophageal adenocarcinoma have also suggested that BIRC2, BIRC3, MMP12, MYC, PVT1, and YAP1 may be ecDNA-related oncogenes." (PMID 40569942, 2025).
renal fibrosis (7 papers, 2013 to 2024). A final common manifestation of a wide variety of chronic kidney diseases characterized by glomerulosclerosis and tubulointerstitial fibrosis. "For renal fibrosis, the lncRNA plasmacytoma variant translocation 1 gene (PVT1) was found to be highly expressed in a variety of renal cell types." (PMID 30287731, 2018). "Knockdown of lncRNA PVT1 inhibited the progression of renal fibrosis via regulation of TGF-β signaling, downregulation of the expression of α-SMA, upregulation of the expression of E-cadherin, and via miR-181a-5p." (PMID 37190024, 2023). "The positive association between PVT1 and TGF-β1 expression shown in the present study has suggested that silencing of PVT1 suppresses TGF-β1-mediated renal fibrosis in DN." (PMID 36359234, 2022). "A recent study has shown that PVT1 inhibition suppressed renal fibrosis through inactivation of TGF-β signalling in UUO-induced murine model." (PMID 36359234, 2022). "LncRNA PVT1 inhibits the progression of renal fibrosis by inactivating the TGF-β signaling pathway." (PMID 39030535, 2024). "The expression of PVT1 lncRNA is significantly upregulated in renal fibrosis." (PMID 37190024, 2023). "Recent studies have suggested that PVT1 promotes DN by increasing extracellular matrix (ECM) accumulation, accelerating podocyte injury and apoptosis, and promoting epithelial-mesenchymal transition (EMT) preceding renal fibrosis." (PMID 36359234, 2022). "Overexpression of lncRNA PVT1 induced by hyperglycemic conditions promotes the expression of primary components of glomerular ECM, including plasminogen activator inhibitor 1, and TGF-β1, FN1 in mesangial cells, thus indicating the positive role of PVT1 in renal fibrosis." (PMID 32752143, 2020). "Knockdown of PVT1 significantly reduced mRNA and protein levels of FN and COL4A1, as well as TGF-β1 and PAI-1, suggesting that PVT1 might affect ECM proteins production in renal fibrosis." (PMID 30287731, 2018).
cardiac hypertrophy (6 papers, 2017 to 2023). "Pvt1 has been associated with radiation resistance in cancer cells and cardiac hypertrophy in cardiomyocytes." (PMID 34364390, 2021). "Circ PVT1 was a inhibitor of miR-203, promoting bladder outlet obstruction-induced bladder hypertrophy and fibrogenesis." (PMID 37744239, 2023). "Besides, Pvt1 has also been found to be essential for cardiomyocytes size maintenance and cardiac hypertrophy development." (PMID 29383134, 2017).
diffuse large B-cell lymphoma (6 papers, 2016 to 2024). "Further, two independent variants of PVT1 (rs13255292 and rs4733601) were associated with diffuse large B-cell lymphoma (DLBCL), with genome-wide significance." (PMID 38384455, 2024). "Only one study testified rs13255292 in diffuse large B-cell lymphoma (DLBCL); by contrast, it was found that T allele PVT1 rs13255292 was the risk of DLBCL." (PMID 34200314, 2021). "As for PVT1 (also termed LINC00079), a GWAS analysis has identified that its variants rs13255292 and rs4733601 are associated with the susceptibility of diffuse large B cell lymphoma." (PMID 32523949, 2020). "A number of genome-wide association studies on Hodgkin’s lymphoma (HL), diffuse large B cell lymphoma (DLBCL) and follicular lymphoma (FL) identified novel susceptibility loci at 8q24.21 near or in the PVT1 gene." (PMID 32228602, 2020). "Our NGS data identified Igh translocation partners, c-myc and Pvt-1, which are often observed in BL and a subset of diffuse large B cell lymphomas." (PMID 26740101, 2016).
epilepsy (6 papers, 2020 to 2025). A brain disorder characterized by episodes of abnormally increased neuronal discharge resulting in transient episodes of sensory or motor neurological dysfunction, or psychic dysfunction. "In animal experiments, PVT1 has been found to promote neuronal cell damage and neuroinflammation induced by epilepsy by regulating the FOXD3/SCN2A pathway mediated by miR-488-3p." (PMID 39976094, 2025). "Silencing PVT1 also increases the expression level of BDNF in the hippocampal tissue of rats with epilepsy, suggesting that PVT1 plays a role in synaptic remodeling." (PMID 39976094, 2025). "Previous evidence has illustrated that PVT1 exerts a promoting effect on cell apoptosis and inflammation in epilepsy." (PMID 37817266, 2023). "The involvement of lncRNA PVT1 in epilepsy has revealed its role in promoting apoptosis in neuronal cells by modulating the miR-488-3p/FOXD3/SCN2A axis." (PMID 37653173, 2023). "The involvement of lncRNA PVT1 in epilepsy has revealed its role in promoting neuroinflammation by modulating the miR-488-3p/FOXD3/SCN2A axis." (PMID 37653173, 2023). "For example, PVT1 was shown to act via the Wnt pathway to suppress astrocyte activation and induce BDNF expression in hippocampal tissues from epilepsy cases." (PMID 32404536, 2020). "Results of pre-clinical studies showed that the expressions of LncRNA H19 and LncRNA X inactive specific transcript (XIST) were up-regulated, while the expressions of LncRNA PVT1, LncRNA CACS2, and LncRNA UCA1 were down-regulated in epilepsy animal or cell models." (PMID 36278003, 2022). "The down-regulated LncRNA PVT1, LncRNA CACS2, and LncRNA UCA1 could, respectively, regulate the downstream proteins including BDNF, PTEN, or JAK to promote the activation of astrocytes and the progression of epilepsy." (PMID 36278003, 2022).
head and neck squamous cell carcinoma (6 papers, 2017 to 2024). A squamous cell carcinoma that arises from any of the following anatomic sites: lip and oral cavity, nasal cavity, paranasal sinuses, pharynx, larynx, and salivary glands. "The PVT1 gene is highly expressed in numerous types of cancers, such as head and neck squamous cell carcinoma (HNSCC)." (PMID 30961610, 2019). "Moreover, It has been reported that the prognosis of patients with head and neck squamous cell carcinoma showing high PVT1 expression was poor, and we also found that PVT1 was upregulated in OSF specimens." (PMID 39320020, 2024).
oral squamous cell carcinoma (6 papers, 2020 to 2026). "PVT1 was further associated with proliferation and cisplatin resistance in oral squamous cell carcinoma." (PMID 35328496, 2022). "Another report indicates that overexpression of GLUT1 is regulated by lncRNA-plasmacytoma variant translocation 1 (PVT1) through the PVT1/miR−150−5p/GLUT1 signaling axis to promote cell proliferation and invasion and inhibit apoptosis in oral squamous cell carcinoma." (PMID 35992779, 2022).
triple-negative breast carcinoma (6 papers, 2019 to 2023). An invasive breast carcinoma which is negative for expression of estrogen receptor (ER), progesterone receptor (PR), and human epidermal growth factor receptor 2 (HER2). "Further research found that PVT1 can promote the proliferation, invasion and migration of triple-negative breast cancer cells." (PMID 36941464, 2023). "We have observed that siRNA targeting of PVT1 exon 9 in claudin-low triple negative breast cancer cells resulted in re-expression of claudin 4 protein, and inhibition of migration." (PMID 33801373, 2021). "In this study, we aimed to assess the role of PVT1 exon 9 in triple negative breast cancer cells." (PMID 33801373, 2021).
uveal melanoma (6 papers, 2017 to 2025). A melanoma derived from melanocytes of the uveal tract. "To further verify the specificity of the prognostic value of PVT1 in uveal melanoma, we also examined its expression profile and the association with OS in patients with primary skin cutaneous melanoma in TCGA." (PMID 29244840, 2017). "Since the expression of PVT1 was associated with malignant behaviors of uveal melanoma, we determine to assess its prognostic value." (PMID 29244840, 2017). "In univariate analysis, we found that epithelioid cell dominant uveal melanoma, extrascleral extension, high PVT1 expression and low PVT1 DNA methylation were associated with unfavorable OS." (PMID 29244840, 2017). "The association between PVT1 expression and the clinicopathological parameters in patients with primary uveal melanoma in TCGA." (PMID 29244840, 2017). "Aberrant PVT1 expression is associated with malignant behaviors of uveal melanoma and might independently predict poor OS." (PMID 29244840, 2017). "Wu and colleagues have shown that lncRNA PVT1 was overexpressed in UM tissues and that silencing of this non-coding RNA suppressed the proliferation, migration, and invasion of uveal melanoma cell lines in vitro." (PMID 40406621, 2025). "In a similar way, in vivo silencing of lncRNA PVT1 reduced the tumorigenic ability of uveal melanoma in nude mice." (PMID 40406621, 2025). "Investigating the lncRNA PVT1 mechanism in uveal melanoma (UM) cell lines, it was found that suppressing lncRNA PVT1 effectively reduced the clonogenic ability of the cells." (PMID 39777348, 2024). "Through investigation of the lncRNA PVT1 mechanism in uveal melanoma (UM) cell lines, it was revealed that the clonogenic capacity of cells significantly decreased after silencing lncRNA PVT1." (PMID 38193829, 2024). "For instance, the EA lncRNA PVT1 expression was strongly and negatively correlated with its methylation status in uveal melanoma." (PMID 34222227, 2021). "By performing univariate and multivariate analysis, we found that high PVT1 expression was an independent predictor of poor OS in patients with uveal melanoma (HR: 12.015, 95%CI: 1.854–77.876, p = 0.009)." (PMID 29244840, 2017). "Among the 80 cases of primary uveal melanoma, 14 cases (17.5%) had PVT1 high-amplification (+2) and 47 cases (58.8%) had amplification (+1)." (PMID 29244840, 2017). "PVT1 DNA amplification was less common in metastatic skin melanoma (190/366, 51.9%) than in uveal melanoma (61/80, 76.3%)." (PMID 29244840, 2017). "By examining copy number alterations in TCGA-UVM, we found that 61 out of 80 cases (76.3%) of primary uveal melanoma had PVT1 amplification." (PMID 29244840, 2017). "By using the deep sequencing data in TCGA, we tried to explore the mechanisms of PVT1 dysregulation in uveal melanoma." (PMID 29244840, 2017). "Multivariate analysis showed that older age (>60) (HR: 2.599, 95%CI: 1.049–6.437, p = 0.039), epithelioid cell dominant uveal melanoma (HR: 4.385, 95%CI: 1.514–12.703, p = 0.006) and high PVT1 expression (HR: 12.015, 95%CI: 1.854–77.876, p = 0.009) were independent predictors for poor OS." (PMID 29244840, 2017). "Therefore, the expression of PVT1 might serve as a valuable and specific prognostic biomarker in uveal melanoma." (PMID 29244840, 2017). "In addition, we also observed different levels of copy number alterations and methylation status between uveal melanoma and skin cutaneous melanoma, which indicate that PVT1 dysregulation might be cancer-specific." (PMID 29244840, 2017). "Based on these findings, we infer that PVT1 expression is modulated by both DNA amplification and methylation and its expression might serve as a valuable and specific prognostic biomarker in terms of OS in uveal melanoma." (PMID 29244840, 2017).
uveal melanoma (continued). "Interestingly, by analyzing the DNA methylation status of PVT1, we observed a strong negative correlation between PVT1 expression and its methylation (Pearson's r = -0.712, Spearman’s r = -0.806), suggesting that DNA methylation status can also influence PVT1 expression in uveal melanoma." (PMID 29244840, 2017).
gestational diabetes (5 papers, 2021 to 2024). Carbohydrate intolerance first diagnosed during pregnancy. "Another study highlighted that reduced lncRNA plasmacytoma variant translocation 1 (PVT1) placental levels in gestational diabetes mellitus (GDM) and PE patients compared to healthy placenta hindered trophoblastic invasion and proliferation." (PMID 39665023, 2024). "The downregulated PVT1 is involved in gestational diabetes and preeclampsia via the regulation of human trophoblast cells." (PMID 36874406, 2023). "Besides, it was also found that the PVT1 expression was lower in the gestational diabetes mellitus and preeclampsia placentas than normal placentas." (PMID 35501901, 2022). "The reverse tendency, downregulation of PVT1, was observed in gestational diabetes mellitus (GDM) and PE placentas." (PMID 33923632, 2021).
kidney injury (5 papers, 2018 to 2021). Trauma to the kidney. "The interaction between NEAT1, PVT1, miR-429, miR-139-5p, and miR-23b-3p may regulate CaOx-induced kidney injury via CCL7 and ROBO2." (PMID 34938320, 2021). "Further, lncRNA PVT1 promotes LPS-induced septic acute kidney injury by binding to TNF-α45." (PMID 31285427, 2019). "Therefore, PVT1 can promote the development of LPS- and vancomycin-induced kidney injury." (PMID 34563213, 2021). "Curcumin could protect LPS-induced septic acute kidney injury by suppressing PVT1 expression." (PMID 34563213, 2021).
neuroblastoma (5 papers, 2009 to 2024). Neuroblastoma (NB) is the most common solid, extracranial childhood tumor. "Therefore, we investigated whether this Qki-Pvt1 axis is also functional in mouse cells by knocking down the three major Qki isoforms (Qki-5, Qki-6, Qki-7) using siRNA in Neuro-2a neuroblastoma cells." (PMID 31357500, 2019). "Many transformed cell types, including neuroblastomas, express PVT1 and do not express MYC." (PMID 19419571, 2009).